IL34 (interleukin 34)
Diseases named in the same sentence as IL34 in open-access papers (continued):
Sharing a sentence is not in itself a finding about the gene and the disease.
glioma (4 papers, 2015 to 2024). A benign or malignant brain and spinal cord tumor that arises from glial cells (astrocytes, oligodendrocytes, ependymal cells). "Although these findings suggest that CSF-1 and IL-34 are susceptible to regulation, anti-CSF-1R therapy warrants further study for effective use in glioma treatment." (PMID 37153567, 2023). "KR158B glioma cells were plated at three densities (50k, 100k, and 200k) and conditioned media was subsequently analyzed after 24 h for M-CSF, IL34, and GM-CSF." (PMID 39272914, 2024). "Our findings show that glioma-secreted M-CSF and IL-34 drive the differentiation of naïve monocytes into functionally T-cell-suppressive M-MDSCs." (PMID 39272914, 2024). "Taken together, these data establish that M-CSF and IL-34 are secreted by glioma cells in both human and murine GBM." (PMID 39272914, 2024). "Like M-CSF inhibition, IL-34 neutralization alone (1 ug/mL of anti-IL-34) was unable to completely prevent M-MDSC differentiation from glioma-conditioned media." (PMID 39272914, 2024). "While CSF-1R, CSF-1 and IL-34 directly support tumor cell growth, CSF-1, highly expressed by glioma cells, effectively promotes macrophage recruitment and indirectly promotes malignant pathogenesis via GAM interactions." (PMID 37153567, 2023). "Thus, blocking CSF-1 or IL-34 signaling by inhibition of the common receptor CSF-1R could be an innovative treatment strategy, as shown in the glioma model." (PMID 26098772, 2015). "Glioma-secreted CSF1R ligands M-CSF and IL-34 were determined to be key drivers of M-MDSC differentiation." (PMID 39272914, 2024). "This highlights the instrumental role of glioma-derived CSF1 and IL-34 in the differentiation of M-MDSCs, as blocking the CSF1R axis prevents expansion of the M-MDSC population in whole bone marrow." (PMID 39272914, 2024). "In this study, we found that glioma-secreted CSF1R ligands, M-CSF and IL-34, promote M-MDSCs to suppress CD8 T cells." (PMID 39272914, 2024). "Glioma-secreted CSF1R ligands M-CSF and IL-34 were identified as key drivers of M-MDSC differentiation while adenosine and iNOS pathways were implicated in the M-MDSC suppression of T cells." (PMID 39272914, 2024). "We found that KR158B glioma cells secrete CSF1R ligands M-CSF and IL-34." (PMID 39272914, 2024). "Having determined that glioma-derived M-CSF and IL-34 drive M-MDSC differentiation and GM-CSF and IL-6 are present in the glioma microenvironment, whole bone marrow was harvested, and cells were cultured in the presence of glioma-conditioned media and exogenous GM-CSF and IL-6." (PMID 39272914, 2024). "Therefore, the use of CSF1R and CSF1 inhibitors in glioma might have differential effects, as the downstream signaling events triggered by CSF1 and IL‐34 are distinct." (PMID 29038312, 2017).
HIV-1 infection (4 papers, 2019 to 2025). The type species of lentivirus and the etiologic agent of acquired immunodeficiency syndrome (AIDS). "IL-34-induced macrophages were characterized by better resistance to HIV-1 infection than CSF1-differentiated cells." (PMID 33408768, 2021). "In humanized mouse models, IL-34-differentiated microglia acted as a reservoir for virus particles, promoting the persistence of HIV-1 infection." (PMID 33408768, 2021). "It was suggested that peripheral blood monocytes differentiated in presence of IL-34 had increased resistance to HIV-1 infection over macrophage colony stimulating factor (MCSF) derived macrophages." (PMID 30832693, 2019). "In contrary, both MCSF and IL-34 enhance HIV-1 infection in human microglia in vitro." (PMID 30832693, 2019).
Insulin resistance (4 papers, 2021 to 2023). Increased resistance towards insulin, that is, diminished effectiveness of insulin in reducing blood glucose levels. "Interleukin-34 (IL-34) is a cytokine that has been found to be expressed on adipocyte, and to be positively correlated with insulin resistance." (PMID 37072577, 2023). "Both drugs have improved insulin sensitivity so they can be very useful for patients with high insulin resistance, with glimepiride more recommended for patients with high level of IL-34." (PMID 37072577, 2023). "IL-34 was found to significantly inhibits insulin-stimulated glucose transport in human differentiated adipocyte, which may explain its role in insulin resistance and making it a suitable marker to reflect insulin resistance status in T2DM patients." (PMID 37072577, 2023). "This study aims to compare the effects of Dapagliflozin versus Glimepiride on glycemic control, insulin resistance, and biomarkers as (extracellular domain of insulin regulated aminopeptidase) IRAPe, (interleukin-34) IL-34, and (N-terminal pro b-type natriuretic peptide) NT-proBNP." (PMID 37072577, 2023).
liver disease (4 papers, 2016 to 2023). "In the present study, we evaluate circulating and intra-hepatic IL-34 in HBV related liver diseases." (PMID 35347503, 2023). "The usefulness of IL-34 as a marker of fibrosis in other types of liver disease is yet to be proven." (PMID 27363523, 2016). "Thus, it was explored that the correlation among IL-34, MCSF and TAMs during the development of HBV-HCC at the different stages, particularly, the kinetics of IL-34 during the progression/development of HBV related liver diseases." (PMID 35347503, 2023). "However, as observed in other tissues, in pathogenic situations IL-34 is capable of inducing macrophage pro-inflammatory polarization with a negative impact on the severity of liver diseases." (PMID 33408768, 2021). "In conclusion, the current study improves our understanding of the role of IL-34 and AFP in HBV related liver disease." (PMID 35347503, 2023).
osteoporosis (4 papers, 2021 to 2025). A condition of reduced bone mass, with decreased cortical thickness and a decrease in the number and size of the trabeculae of cancellous bone (but normal chemical composition), resulting in increased fracture incidence. "Radiographic analysis and histological evaluation were performed to confirm the therapeutic effects of IL-34 in fracture healing and osteoporosis." (PMID 33947456, 2021). "While IL-34 has been shown to activate OC formation, it is worth nothing that IL-34 has no impact on both in vitro osteoclastogenesis and osteoporosis in ovariectomized rat." (PMID 37895023, 2023). "However, the additional IL-34 has no influence on both osteoclastogenesis of mBMMs in vitro and osteoporosis of OVX model of rat in vivo." (PMID 33947456, 2021). "Collectively, our study demonstrate that low-dose IL-34 regulates osteogenesis of hBMSCs partly via the PIK/AKT and ERK signaling pathway and enhances fracture healing, with neither promoting nor preventing osteoclastogenesis in vitro and osteoporosis in vivo." (PMID 33947456, 2021). "Our results founded that low-dose IL-34 regulates osteogenesis of hBMSCs partly via the PIK/AKT and ERK signaling pathway and enhances fracture healing, with neither promoting nor preventing osteoclastogenesis in vitro and osteoporosis in vivo." (PMID 33947456, 2021). "Collectively, our study first demonstrate that low-dose IL-34 regulates osteogenesis of hBMSCs partly via the PIK/AKT and ERK signaling pathway and enhances fracture healing, with neither promoting nor preventing osteoclastogenesis in vitro and osteoporosis in vivo." (PMID 33947456, 2021).
prion disease (4 papers, 2020 to 2021). A transmissible disease that is caused by a protein that is able to induce abnormal folding of normal cellular proteins, leading to characteristic spongiform brain changes, which are associated with neuronal loss without an inflammatory response. "Conditional mice for IL-34 experienced an acceleration of prion infection compared to healthy mice, suggesting that IL-34 attenuates prion disease by inducing the expansion of microglia populations, which play a neuroprotective role in prion pathogenesis." (PMID 33408768, 2021). "In this study, we evaluate the inhibition of IL-34 as a novel strategy to reduce microglial proliferation in the ME7 model of prion disease." (PMID 33162994, 2020). "In this study we explored the effect of inhibition of IL-34 on blood monocytes, systemic tissue macrophages, and microglia in health and neurodegenerative disease, modeled by a murine model of prion disease." (PMID 33162994, 2020). "IL-34 antibodies were stereotactically injected into the hippocampus 12 weeks after induction of prion disease, a timepoint of pronounced microglia proliferation, and brains were collected 1 week after injection." (PMID 33162994, 2020). "IL-34 and Syndecan-1 also increased in APP cKO, especially at 6 months of age, and IL34 was recently proposed to be the main brain factor to stimulate proliferation of microglia in the ME7 model of prion disease." (PMID 33402196, 2021). "IL-34 levels were around 300 times higher in the naïve brain than CSF-1 levels, but not changed in the context of prion disease or after IL-34 antibody treatment." (PMID 33162994, 2020). "It is possible that in the genetically modified mice with a constitutive loss of function of IL-34, CSF-1 compensates for the absence of IL-34 and drives proliferation through CSF1R to expand the microglial population in prion disease." (PMID 33162994, 2020).
psoriasis (4 papers, 2018 to 2024). An autoimmune condition characterized by red, well-delineated plaques with silvery scales that are usually on the extensor surfaces and scalp. "This is aligned with our previous observations with reduced IL34 levels in epithelial hyperplasia conditions such as CIN3, psoriasis and eczema." (PMID 39619016, 2024). "This aligns with our previous findings of reduced IL34 transcripts in CIN3, psoriasis and eczema." (PMID 39619016, 2024). "We previously showed that IL34 mRNA expression is downregulated in cutaneous and mucosal squamous epithelial hyperplasia, including high‐grade cervical intraepithelial neoplasia (CIN3), psoriasis and eczema." (PMID 39619016, 2024).
renal fibrosis (4 papers, 2018 to 2025). A final common manifestation of a wide variety of chronic kidney diseases characterized by glomerulosclerosis and tubulointerstitial fibrosis. "Previous basic experiments on the kidney also showed that compared to IL-34–/– mice, more tubular pathology and leukocytes were detected in the interstitium after I/R injury, and more severe renal fibrosis was found in the chronic phase in wild-type mice." (PMID 30050466, 2018). "The critical role of IL-34 and CXCL16 in renal fibrosis was established by previous studies." (PMID 40131554, 2025). "In this study, we found that changes in a rat model of hypertensive kidney disease, including the expression of iPT cells, SPP1, IL34, and PDGFB, strongly correlated with renal fibrosis in human kidney samples obtained from patients with hypertensive and diabetic kidney disease." (PMID 37906287, 2024). "Previous studies established the key role of IL-34 and CXCL16 in renal fibrosis." (PMID 38152332, 2023).
anemia (3 papers, 2016 to 2018). A reduction in the number of red blood cells, the amount of hemoglobin, and/or the volume of packed red blood cells. "Higher IL-34 level was also associated with poorer general condition, such as anemia and low serum albumin level, leading to more severe cardiac dysfunction." (PMID 30050466, 2018). "The present study demonstrated that higher serum IL-34 levels were associated with poorer renal function and more severe anemia in patients with CHF." (PMID 27982136, 2016).
chronic heart failure (3 papers, 2016 to 2022). "In patients with normal cardiac function and chronic heart failure, higher serum IL-34 levels were significantly associated with more severe coronary artery disease (CAD)." (PMID 36233294, 2022). "We also found that serum IL-34 levels were significantly associated with poor prognosis in patients with chronic heart failure, especially in those with renal impairment." (PMID 30050466, 2018). "As an additional ligand of Colony Stimulating Factor-1 Receptor (CSF-1R), interleukin-34 (IL-34) has been identified as a pro-inflammatory cytokine participating in chronic heart failure (CHF)." (PMID 27982136, 2016).
chronic hepatitis B (3 papers, 2019 to 2024). "We evaluated serum IL‐34 levels in chronic hepatitis B (CHB) patients, HBV‐related HCC patients and HBV‐negative HCC patients." (PMID 31621133, 2019).
Cognitive impairment (3 papers, 2017 to 2025). Abnormal cognition is characterized by deficits in thinking, reasoning, or remembering. "On the other hand, some studies have described an association between cognitive impairment and decreased serum levels of IL-34, particularly in vascular dementia." (PMID 40389754, 2025). "In this study, we investigated the levels of the macrophage growth factors IL-34 and CSF-1 in three biofluids at different stages of cognitive impairment and found higher levels of IL-34 in saliva from AD patients compared with controls and subjects with SCI." (PMID 40389754, 2025). "We analyzed the levels of IL-34 and CSF-1 in saliva, CSF, and plasma in participants with different stages of cognition impairment." (PMID 40389754, 2025). "After adjusting for various demographic features, the relationship between IL-34 and the cognitive impairment of VaD patients is still significant, with an OR of 2.171 (β = 0.276, p = 0038)." (PMID 34095310, 2021). "As far as we know, this is the first research report that uses serum IL-34 as an index to predict cognitive impairment in VaD patients." (PMID 34095310, 2021). "Therefore, we aimed to investigate the salivary levels of IL-34 and CSF-1 in different stages of cognitive impairment, and in relation to periodontal status." (PMID 40389754, 2025). "The gene expression of CSF-1 and IL-34 in brain tissue during health and cognitive impairment remains to be fully elucidated, however one study reported increased gene expression of CSF-1 and CSF-1R, and reduced expression of IL-34 in human brain samples from AD patients." (PMID 40389754, 2025). "Serum IL-34 levels in VaD patients were significantly reduced, which may be an independent predictor of cognitive impairment in VaD patients." (PMID 34095310, 2021). "Therefore, the main purpose of our study is to explore the relationship between IL-34 and cognitive impairment in VaD patients, in order to provide potential targets and drugs for the treatment of VaD." (PMID 34095310, 2021). "In other words, VaD patients with low serum IL-34 levels may have more severe cognitive impairment." (PMID 34095310, 2021). "The purpose of this study is to determine whether IL-34 is involved in cognitive impairment of VaD." (PMID 34095310, 2021). "Here, we found an increase in salivary IL-34 levels in MCI compared with controls, suggesting that it may be indicative of cognitive impairment before the onset of AD." (PMID 40389754, 2025).
depression (3 papers, 2019 to 2023). "Moreover, IL-34 may be a biological diagnostic marker of depression." (PMID 36970289, 2023). "EVs play a vital role in the pathogenesis of depression by transporting miRNA and effector molecules such as BDNF, IL34." (PMID 35401216, 2022). "This means that brain-derived IL-34, SYP, and TNFR1 might be related to depression-like behaviour and depression symptoms." (PMID 36970289, 2023).
hepatoblastoma (3 papers, 2022 to 2024). Hepatoblastoma (HB) is a malignant hepatic tumor and is the most common pediatric liver cancer. "IL‐34 expression was potentially linked to not only cell proliferation and chemoresistance in hepatoblastoma in autocrine manner, but also protumor TME development by inducing TAM infiltration." (PMID 35132816, 2022). "It has also been shown that the co-culture of hepatoblastoma cells with macrophages induced IL-34 overexpression in cancer cells via BRD4 signaling, further supporting the role of BRD4 in the control of IL-34 expression." (PMID 39451216, 2024). "Our in vitro study using hepatoblastoma cell lines and HMDMs showed that direct contact with macrophages induced tumor cell proliferation and Brd4 expression, which induced IL‐34 expression." (PMID 35132816, 2022). "We next examined if IL‐34 in hepatoblastoma cells was regulated by Brd4 by using the Brd4 inhibitor, JQ‐1." (PMID 35132816, 2022). "In conclusion, a high density of CD163‐positive TAMs was seen in embryonal components of hepatoblastoma cases, and Brd4‐induced IL‐34 production was suggested to induce infiltration of TAMs in embryonal components." (PMID 35132816, 2022). "Hepatoblastoma cell-derived exosomes can induce Huh6 cells to overexpress interleukin-34 (IL-34) via Brd4 signaling and induce drug resistance in an autocrine manner." (PMID 35571530, 2022). "IL‐34 may be a promising target for anti‐hepatoblastoma therapy." (PMID 35132816, 2022). "In addition, Brd4 and IL‐34 may be novel markers for embryonal components of hepatoblastoma cases." (PMID 35132816, 2022).
Hypertension (3 papers, 2016 to 2023). The presence of chronic increased pressure in the systemic arterial system. "Multivariable linear regression analysis further verified a significant relationship between IL-34 level and NT-proBNP level (β = 0.171, P < 0.001) after adjusting for age, sex, BMI, history of hypertension, history of DM, and levels of hsCRP, hemoglobin, albumin, HbA1c, as well as eGFR." (PMID 30050466, 2018).
ischemia (3 papers, 2016 to 2025). A hypoperfusion of the BLOOD through an organ or tissue caused by a PATHOLOGIC CONSTRICTION or obstruction of its BLOOD VESSELS, or an absence of BLOOD CIRCULATION. "The effects of IL-34 on MI/R injury should be investigated and verified on different time point of ischemia and reperfusion, and different type of animals." (PMID 39883639, 2025). "First, IL-34, generated by renal tubule epithelial cells (TECs), is up-regulated in kidney and serum during ischemia in a murine model of kidney ischemic reperfusion injury." (PMID 27982136, 2016).
liver cancer (3 papers, 2023). An epithelial or non-epithelial malignant neoplasm that arises from the liver. "TACE (localized chemotherapy), therefore, effectively induces malignant cellular damage inside the liver cancer, subsequently down-regulating HCC cellular function, including IL-34 production." (PMID 35347503, 2023).
multiple myeloma (3 papers, 2019 to 2021). "IL-34 from TECs has a physiological property as a Mø mediator, and the anti-mouse IL-34 Ab, i.e., polyclonal sheep IgG produced in response to a mouse myeloma cell line, functioned as a nAb." (PMID 33428678, 2021). "Moreover, in multiple myeloma (MM), IL-34 accelerates MM-induced osteoclast formation from monocytes and increases the severity of bone lesions, whereas, in sporadic vestibular schwannoma, IL-34 expression is not related to clinicopathologic characteristics and tumor growth." (PMID 31968663, 2020).
non-alcoholic fatty liver disease (3 papers, 2016 to 2021). "For the screening and follow-up of patients with nonalcoholic fatty liver disease, we demonstrated that interleukin 34 is a feasible fibrosis marker." (PMID 29201774, 2017).